OIP5-AS1 (OIP5 antisense RNA 1)
Synonyms: cyrano; linc-OIP5; OIP5
Gene: Long non-coding RNA gene on chromosome 15 (41,283,958 to 41,322,392, forward strand). Ensembl gene ENSG00000247556.
Diseases named in the same sentence as OIP5-AS1 in open-access papers:
OIP5-AS1 is named in the same sentence as 11 diseases in open-access papers, as found by Europe PMC text mining. Sharing a sentence is not in itself a finding about the gene and the disease. The quoted sentences say what the papers report.
multiple myeloma (2 papers, 2020 to 2024). "Yang and colleagues found an unfavorable relationship between the long non-coding RNA OIP5 antisense RNA 1 (lncRNA OIP5-AS1), located on chromosome 15q15.1, and the high expression levels of miR-410 in newly diagnosed multiple myeloma." (PMID 38338876, 2024).
ovarian carcinoma (2 papers, 2022 to 2025). A malignant neoplasm originating from the surface ovarian epithelium. "Another work conducted on epithelial ovarian cancer (EOC) identified a novel lncRNA OIP5 antisense RNA 1 (OIP5-AS1)/miR-137/ZNF217 regulatory circuit that accelerates ovarian cancer progression." (PMID 36551531, 2022). "Certain exosomal RNAs, such as OIP5 Antisense RNA 1 (OIP5-AS1), have been studied in other cancer types but are not well-documented in ovarian cancer." (PMID 39891297, 2025).
acute lung injury (1 paper, 2021). A condition of lung damage that is characterized by bilateral pulmonary infiltrates (pulmonary edema) rich in neutrophils, and in the absence of clinical heart failure. "The present study revolves around probing into the function and molecular mechanism of long non-coding RNA OIP5 antisense RNA 1 (lncRNA OIP5-AS1) in modulating acute lung injury (ALI) mediated by sepsis." (PMID 34592882, 2021).
atherosclerosis (1 paper, 2021). A disease characterized by the build-up of fatty material and calcium deposition in the arterial wall resulting in partial or complete occlusion of the arterial lumen. "LncRNA OIP5 antisense RNA 1 (OIP5-AS1) has been found to be associated with the development of atherosclerosis." (PMID 33778018, 2021).
periodontitis (1 paper, 2022). An acute or chronic inflammatory process that affects the tissues that surround and support the teeth. "Long non-coding RNA OIP5 antisense RNA 1 (OIP5-AS1) has been reported to downregulated in the periodontal tissue of patients with periodontitis." (PMID 35546327, 2022).
cancer (2 papers, 2020 to 2025). A tumor composed of atypical neoplastic, often pleomorphic cells that invade other tissues. "OIP5 antisense RNA 1 (OIP5-AS1) has been reported to play important role in the occurrence and development of multiple human cancers." (PMID 32669972, 2020).
OIP5-AS1 also shares sentences with these, for which no sentence is quoted: breast carcinoma (1 paper); glioma (1); lung adenocarcinoma (1); Sepsis (1); tumor (1).